FOXO1 (forkhead box O1)
Diseases named in the same sentence as FOXO1 in open-access papers (continued):
Sharing a sentence is not in itself a finding about the gene and the disease.
cancer (508 papers, 2006 to 2026). A tumor composed of atypical neoplastic, often pleomorphic cells that invade other tissues. "The transcription factors FoxO1 and FoxO3, in particular, have been linked to the emergence and progression of a variety of cancer entities and suggested as therapeutic targets." (PMID 39766892, 2024). "Curiously, single nucleotide somatic mutations of FOXO1 in cancer occur frequently at and near Thr24." (PMID 38519029, 2024). "As for miR-196a-5p, it has been implicated in targeting forkhead box protein O1 (FOXO1) and has been associated with various cancers." (PMID 38139016, 2023). "Previous studies suggested that FoxO1 knockdown protected human cancer cells against death caused by trichostatin A." (PMID 36829992, 2023). "In contrast, the deactivation of FOXO1 in gastric cancer contributes to better outcomes, while its activation in B-cell lymphomas was shown to be associated with cancer progression." (PMID 37821870, 2023). "Most studies have demonstrated that the dysfunction of the FOXO1 signaling pathway is associated with numerous complex molecular cascades in cancer pathophysiology." (PMID 35723050, 2022). "FOXO1’s anti-cancer role is associated with the regulation of critical genes related to cell cycle arrest and cell apoptosis such as p21 Cip1." (PMID 35723050, 2022). "Studies have confirmed that the role of Forkhead box transcription factor-1 (FOXO1) is linked to the role of EZH2 inhibitors in cancer." (PMID 34149432, 2021). "The findings discovered a facilitating role of FOXO1/NDRG1 axis which acted as a downstream factor of cancer‐associated fibroblasts." (PMID 34965023, 2021). "Foxo1 is a key regulator of glucose and lipid metabolism in the liver; therefore, its inactivation is a hallmark of cancer-related metabolic dysregulation." (PMID 33801718, 2021). "We showed previously that MMP11 functions in the regulation of whole-body metabolism through activation of the IGF1/AKT/FoxO1 signaling cascade in a non-cancer context using gain- and loss-of-function genetic-engineered mice models." (PMID 32825455, 2020). "Next, MethylMix-PA also identified hyper-methylation of FOXO1, a transcritionf factor where low expression has been associated with cancer." (PMID 31356589, 2019). "While a number of mechanisms have been suggested for the repression of FOXO1 function during cancer progression 23, the mechanism underlying the transcriptional regulation of FOXO1 in cancer remains poorly understood." (PMID 31410199, 2019). "Our findings suggest that EZH2 repression of FOXO1 can be targeted by EZH2 inhibitor as a monotherapy for PTEN-proficient cancers or in combination with taxane for treatment of cancers with PTEN mutation or deletion." (PMID 31410199, 2019). "To directly assess the impact of cytosolic FoxO1 on autophagy in PC3 cancer cells, we introduced into cells an expression vector containing Flag-tagged FoxO1 modified to have a defective DNA binding mutation, FoxO1-ΔDB." (PMID 25546383, 2014). "Recent studies from our laboratory have shown that loss or down regulation of FOXO1 is associated with aggressive cancer cell phenotype and poor prognosis in cancer patients." (PMID 25062088, 2014). "Typically, inhibition of FOXO1 in cancer is associated with the activation of higher level kinases such as Akt and IKK (IκB kinase)." (PMID 25472505, 2014). "We focused on the mutation of Thr24 of FOXO1, a residue that is frequently mutated in cancer." (PMID 38519029, 2024). "According to the KEGGpathway analysis, genes associated with FOXO1 may have functions in thedevelopment of ‘transcriptional misregulation in cancer'." (PMID 38716982, 2024). "In summary, we show that FOXO1-driven transcriptional and epigenetic programs are associated with engineered and non-engineered T cells that expand, persist and promote clinical responses in patients with cancer." (PMID 38600391, 2024).
cancer (continued). "This raises the possibility that a higher abundance of type I myofibers may be associated with decreased cancer risk; studies using genetic deletion of forkhead box O-1 (FOXO1) further support this possibility." (PMID 38928185, 2024). "Dysregulation of FOXO1 signaling is often associated with cancer progression." (PMID 38994962, 2024). "Therefore, we combined miRNA-target (FOXO1) interactions and relevant associations between miRNA and cancer recorded in dbCRAF to map FOXO1-miRNA-cancer associations." (PMID 38406264, 2024). "Since mutations in FOXO1 are often found at AKT phosphorylation sites in cancer, we focused on protein phosphatases as new factors that might modulate FOXO1 phosphorylation." (PMID 38519029, 2024). "Interestingly, we also noted significant PI3K, p-Akt suppression and FoxO1 activation in QNP-treated cancer cells, suggesting the underlying mechanism to be targeted in cancer reduction." (PMID 35890222, 2022). "Interestingly, cancer-associated fibroblasts (CAFs) promote DNM3OS expression in a PDGFβ/PDGFRβ/FOXO1 signaling pathway-dependent manner in ESCC, resulting in enhancing radioresistance." (PMID 36294743, 2022). "The FOXO1 gene has been implicated to be involved in cancer pathways." (PMID 34070979, 2021). "FOXO1 also promotes the expression of miR-145 to control multiple proteins associated with cancer." (PMID 34299605, 2021). "In addition, we also examined the expression of other proteins that are associated with cancer cell apoptosis and autophagy including Foxo1 and Beclin-1." (PMID 31892846, 2020). "Moreover, we showed that both rodent (NIH3T3 and REF52) and human cancer cells (HCT116) transfected with a vector encoding the E1A are characterized by an increased basal level of FoxO1 protein." (PMID 31906031, 2019). "Thus, we identified a novel NUAK1/Akt/FOXO1-3a axis, which may be implicated in cancer progression and chemotherapy efficacy." (PMID 38135881, 2023). "It inhibits the PI3K/Akt/mTOR pathway, essential for cancer cell growth and survival, and induces the nuclear translocation of the FoxO1 protein, affecting various cellular processes." (PMID 40868211, 2025). "This emphasizes that FOXO1 induces the resistance to oxidative stress in cancer cells via transcriptional activation of G6PD." (PMID 41124013, 2025). "This explains how cancer cells rewire their metabolism from glycolysis to the PPP to obtain an adequate supply of the NADPH reductant to detoxify ROS via FOXO1." (PMID 41124013, 2025). "These genes again corresponded to pathways such as longevity, circadian rhythms, autophagy, cancer, and FOXO1 signaling." (PMID 41381594, 2025). "Overall, FoxO1 inhibition is emerging as a strategy in cancer therapy, with various preclinical studies demonstrating its potential across different malignancies." (PMID 39533662, 2025). "FoxO1 inhibition in cancer requires a robust assessment of the inhibitors' specificity and potential toxicity." (PMID 39533662, 2025). "a highly aggressive childhood muscle-derived cancer in which the oncogenic fusion protein paired box 3–forkhead box O1 (PAX3-FOXO1) stimulates the RASSF4 protein expression." (PMID 41007433, 2025). "Studies have shown that microRNAs play essential roles in regulating the PTEN/AKT/FOXO1 axis and especially in regulating cancers." (PMID 39833662, 2025). "In AML and BCP‐ALL, FoxO1 inhibition has shown notable efficacy in reducing cancer stem cell proliferation and cell viability with limited toxicity to healthy cells." (PMID 39533662, 2025). "Mechanistically, UA induced cell cycle arrest and apoptosis while enhancing the expression of key tumor suppressors, including Sirtuin 1 (Sirt1) and Forkhead box protein O1 (FOXO1), both of which are crucial regulators of cancer cell dynamics." (PMID 40568370, 2025). "SIRT2 and HDAC3 can also mediate the deacetylation of FOXO1, inhibiting FOXO1 activity and autophagy and thereby promoting cancer progression." (PMID 39778006, 2025).
cancer (continued). "SOX2 is a transcriptional factor for cancer stemness, whose transcriptional expression is promoted by the accumulated FOXO1, which in turn, stimulates FOXO1 transcription and shapes a positive regulatory loop." (PMID 40746611, 2025). "Here, we found that FOXO1 endows cancer cells with the strong antioxidative capacity and rapid proliferation." (PMID 41124013, 2025). "Collectively, SIRT1-mediated deacetylation of FOXO1 represents a crucial mechanism by which cancer cells evade senescence and apoptosis, while maintaining redox homeostasis." (PMID 41008982, 2025). "FOXO1, involved in the development of various cancers, including hormone-dependent ones, influences androgen synthesis and regulates androgen receptor activity." (PMID 40075208, 2025). "Based on the role of this axis in cancer biology, FOXO1 gene and protein expression levels and its phosphorylated form were studied in the LSCC patients." (PMID 41436994, 2025). "FOXO transcription factors are well-known inhibitors of tumour progression, and FOXO1 has been shown to suppress EMT across various types of cancer." (PMID 39777582, 2025). "In conclusion, our data further demonstrate the antitumor activity of UroA supplementation and discover its efficacy in regulating naïve T cells and enhancing cancer immunosurveillance via FOXO1 activation." (PMID 38626334, 2024). "Of note, recently it was shown that urolithin-A promotes CD8+ T Cell-mediated cancer immunosurveillance via activation of FOXO1." (PMID 39850551, 2024). "FOXO1 has been demonstrated to possess anti-tumorigenic properties in cancer cells, primarily by inducing apoptosis, cell cycle arrest, and autophagy at the transcriptional level." (PMID 38436783, 2024). "In this study, we investigate the effect of UroA on T cells and its potential capacity to improve cancer immunosurveillance and demonstrate that UroA supplementation boosts cancer immunosurveillance by promoting FOXO1-transcriptional activity." (PMID 38626334, 2024). "Urolithin-A, a potent mitophagy inducer, emerges as a promising tool to enhance cancer immunosurveillance by activating the FOXO1 transcription factor in CD8+ T cells." (PMID 38626334, 2024). "To clarify the role of FOXO1 in cancer cells, we first examined the location and frequency of missense mutations in all cancer somatic mutation data obtained from COSMIC." (PMID 38519029, 2024). "Bioinformation analysis with previous researches have established FOXO1 as a downstream target of miR-135b in multiple cancer types." (PMID 39135158, 2024). "We discovered that UroA improved the cancer immune response by activating the transcription factor FOXO1 in CD8+ T cell." (PMID 38626334, 2024). "The suppression of FOXO1 phosphorylation hindered its regulatory functions in sustaining cancer stemness, including the modulation of ALDH1 and IL6." (PMID 39438918, 2024). "The identification of FOXO1 as a key regulator opens new avenues for understanding the role of Zn in cancer biology." (PMID 39247196, 2024). "The relationship between prognosis of pan-cancer and FOXO1 expression wasevaluated using Kaplan-Meier analysis, as per the TCGA database." (PMID 38716982, 2024). "As a firststep, we examined the correlation between FOXO1 expression and OS in variousforms of cancer." (PMID 38716982, 2024). "Our results suggest that FOXO1 represents a major therapeutic axis that can be exploited to improve the efficacy of T-cell-based cancer immunotherapies." (PMID 38600391, 2024).
cancer (continued). "The FOXO1 gene was first discovered in human cancer chromosomal translocation studies, located on 13q14.11, and consisted of 3 exons with a total length of 144,267 nt." (PMID 39021599, 2024). "FOXO1 protein was found to be low/medium expressed in cancer tissue, while medium expression was noticed in normal colon and rectal tissue." (PMID 38891994, 2024). "This diminishes the stability of the FOXO1 protein, promoting cancer cell proliferation, and inhibiting apoptosis." (PMID 39184862, 2024). "MOMP.Sig model integrates pan‐cancer ICI CRISPR screen to identify key molecule FOXO1 for immunotherapy resistance." (PMID 38899748, 2024). "Functional enrichment analysis and gene set enrichment analysis were performed toelucidate the potential biological role of FOXO1 in pan-cancer." (PMID 38716982, 2024). "Nevertheless, furtherinvestigations are required to elucidate the function and mechanism of FOXO1 inall types of cancer." (PMID 38716982, 2024). "Tight junction (TJ) protein cingulin (CGN) and transcription factor forkhead box protein O1 (FOXO1) contribute to the development of various cancers." (PMID 38338691, 2024). "By upregulating the expression of forkhead box protein O1 (FoxO1), it hinders cancer cell proliferation and induces apoptosis." (PMID 38915462, 2024). "In cancer, FoxO1 can regulate many target genes, including those involved in apoptosis, cell cycle arrest, and immune regulation." (PMID 39682478, 2024). "FOXO1-T24E was destabilized compared to WT, suggesting that the unphosphorylated form of FOXO1 observed in cancer cells was more stable than WT." (PMID 38519029, 2024). "In the pan‐cancer cohort, the AUC of the ROC curve for predicting immunotherapy response based on FOXO1 expression levels was 0.66." (PMID 38899748, 2024). "Further investigations are required to elucidate the function andmechanisms of FOXO1 in all types of cancer." (PMID 38716982, 2024). "Foxo1, recognized as a cancer-related transcription factor, is a forkhead box family member as well as one of the downstream molecules of the PI3K–Akt signaling." (PMID 38549224, 2024). "Recent findings suggest a link between FOXO1 and ferroptosis in cancer cells and cardiomyocytes, proposing FOXO1 as a crucial regulator of ferroptosis in multifarious conditions." (PMID 39206719, 2024). "Previous study already identified a link between MAPK1, Dock10 and FoxO1 as a key signalling axis that incorporates MAPK1 signalling to promote cancer progression through induction of EMT, increased invasiveness and resistance to compression." (PMID 37131239, 2023). "Identifying the conditions that dictate WNT pathway regulation by FOXO1 in cancer will allow for a greater understanding of divergent responses to AS1842856 treatment in these settings." (PMID 37584250, 2023). "More generally, defects in each of the players of the LoL-DDR response described here (NF-κB, PARP1, FOXO1, DUOX1 and DUOX2) share common phenotypes, such as defects in cell homeostasis and metabolism, aging and cancer predisposition." (PMID 36869180, 2023). "Intriguingly, the simultaneous conditional deletion of Foxo1, 3, and 4 results in a cancer-prone phenotype." (PMID 37891184, 2023). "In ARMS, up to 80% of cases are characterized by a chromosomal translocation resulting in the formation of PAX3/FOXO1 or PAX7/FOXO1 fusion onco-proteins, key markers of poor prognoses in these cancers." (PMID 37858275, 2023). "Forkhead box O1 (FOXO1) is known as a cancer suppressor and it is able to suppress the NAMPT expression." (PMID 37175631, 2023).
cancer (continued). "This work is the first to highlight FOXO1 as a possible therapeutic target in the poor‐prognosis cancers BBC and GBM." (PMID 36602390, 2023). "NUAK1 was required for the Akt/FOXO1/3a axis, regulating p21CIP1, p27KIP1, and FoxM1 expression and cancer cell survival upon EGFR stimulation." (PMID 38135881, 2023). "It was shown that activation of IGFR/PI3K/AKT pathway by IGF1 resulted in phosphorylation of FOXO1/3 in cardiac stem cells, myotubes or cancer cells." (PMID 37985893, 2023). "FOXO1 has been substantiated as a tumor suppressor gene in cancers and its expression level is positively correlated with the prognosis of BC patients." (PMID 36856518, 2023). "In other cells, such as cancer cells and hepatocytes, FOXO1 is primarily located in the nucleus at homeostatic state; yet it is constitutively located in the cytoplasm in homeostatic β cells and undergoes nucleus translocation in stressed β cells." (PMID 37452039, 2023). "In detail, activated transcription factors, such as FOXO1, HIF1A, STAT3, and JUN, regulate the expression of TGFB1, TGFB3, IL1B, and TNF, promoting cancer hallmarks associated with these ligands." (PMID 37370765, 2023). "Given the role of FOXO1 in promoting stem gene expression in BBC and GBM cells, we examined the impact of FOXO1 inhibition on colony formation in a set of representative cancer cell lines." (PMID 36602390, 2023). "The Human Protein Atlas database has shown that the survival rate of patients with cancers of lower FOXO1 expression is shorter than those of patients with cancers of higher FOXO1 expression in colorectal, renal, and hepatic adenocarcinomas." (PMID 36830954, 2023). "Emerging evidence points to pro‐oncogenic roles for some FOXO factors in cancers such as diffuse large B‐cell lymphoma (DLBCL), in which FOXO1 is commonly mutated to a constitutively nuclear form; these FOXO1 mutations were associated with poor prognosis." (PMID 36602390, 2023). "In contrast, normalization of the ATP1A1 signaling significantly decreased H3K9ac and H3K9me3, in vitro and in vivo, with concomitant nuclear localization of FoxO1, heightening cell autophagy and cancer-cell apoptotic activities in treated HCC cell lines." (PMID 37830582, 2023). "Previous research has shown that miR-196a can enhance the proliferation of cancer cells by targeting FOXO1." (PMID 38067033, 2023). "Several studies have expounded the miR-183 function on the apoptosis, proliferation and invasion of cancers by negatively regulated FOXO1." (PMID 36550935, 2022). "To test this prediction, we first used Western blotting to detect the FOXO1 acetylation level in cancer tissues." (PMID 35126526, 2022). "Through whole transcriptome sequencing followed by assays in vitro, in vivo and using clinical samples, we propose CAP as a promising onco-therapy targeting cancer stemness via the AQP3/FOXO1 axis." (PMID 35637961, 2022). "FOXO1 regulates the expression of a number of cancer-related genes, such as p27KIP1, p21WAF1, cyclin D1, cyclin D2, FasL, p130, and Bim." (PMID 36293387, 2022). "FOXO1 is a tumor repressor that is believed to be down-regulated in cancer through negative regulation by the enhancer of zeste homolog 2 (EZH2)." (PMID 35577773, 2022). "Inhibited FOXO1 phosphorylation retarded its regulatory activities in maintaining cancer stemness including ALDH1 and IL6." (PMID 35637961, 2022). "FoxO1 is reportedly involved in the mechanism of drug resistance, in which elevated ROS makes cancer cells more sensitive to chemotherapy." (PMID 35865479, 2022). "Extracellular signal-regulated kinase 2 (ERK2) has been reported to phosphorylate FOXO1 at many residues in human cancer cells." (PMID 35453780, 2022). "Elevated levels of Foxo1 have long been implicated in the pathogenesis of metabolic disorders and drug resistance in certain types of cancers, and small molecule inhibitors of Foxo1 have been proposed as a form of pharmacologic treatment." (PMID 36742198, 2022).